FBXO24 (F-box protein 24)
Description:
Substrate recognition component of an SCF (SKP1-CUL1-F-box protein) E3 ubiquitin-protein ligase complex that mediates the ubiquitination and subsequent proteasomal degradation of target proteins. Specifically recognizes the deacetylated form of nucleoside diphosphate kinase A/NME1 and targets it for ubiquitin-mediated degradation. Functions as a key regulator of cell proliferation by targeting PRMT6 for ubiquitination and proteasomal degradation, leading to cell cycle inhibition. Also mediates 'Lys-6'-linked polyubiquitination of the mitochondrial S-adenosylmethionine transporter SLC25A26, targeting it for degradation and thereby maintaining mitochondrial function during spermiogenesis (By similarity). Promotes ubiquitination and degradation of mitochondrial aspartyl-tRNA synthetase DARS2, contributing to immunosuppressive activity. In the nucleus, targets FOXK2 for ubiquitin-mediated degradation, a process that critically modulates mitochondrial respiration and cellular bioenergetics in lung epithelial cells.
Synonyms: FBX24
Tractability: No criterion of Open Targets' tractability assessment is met for any kind of drug.
Gene: Protein-coding gene on chromosome 7 (100,583,982 to 100,601,117, forward strand). Ensembl gene ENSG00000106336.
Subcellular location: Mitochondrion; Nucleus
Gene Ontology:
Molecular function: protein binding; ubiquitin-like ligase-substrate adaptor activity; ubiquitin-protein transferase activity
Biological process: SCF-dependent proteasomal ubiquitin-dependent protein catabolic process; protein ubiquitination
Cellular component: mitochondrion; nucleus; cytoplasm; SCF ubiquitin ligase complex; ubiquitin ligase complex
Genetic constraint (gnomAD): Loss-of-function variants: 30 observed, 63.5 expected, observed/expected ratio (o/e) 0.47, 90% interval 0.35 to 0.64. The upper end of that interval is the gene's LOEUF score, 0.64, which puts it in group 2 of 6, group 1 being the genes least tolerant of losing a copy. Missense variants: 624 observed, 789.96 expected, observed/expected ratio (o/e) 0.79, 90% interval 0.74 to 0.84. Synonymous variants: 300 observed, 315.15 expected, observed/expected ratio (o/e) 0.95, 90% interval 0.87 to 1.05.
Homologues: Orthologues: chimpanzee FBXO24 (98% identical), macaque FBXO24 (96% identical), dog FBXO24 (91% identical), pig FBXO24 (89% identical), mouse Fbxo24 (87% identical), rat Fbxo24 (87% identical), rabbit FBXO24 (87% identical), guinea pig FBXO24 (84% identical), tropical clawed frog fbxo24 (44% identical). Paralogues in human: MYCBP2 (25% identical).
Diseases named in the same sentence as FBXO24 in open-access papers:
FBXO24 is named in the same sentence as 8 diseases in open-access papers, as found by Europe PMC text mining. Sharing a sentence is not in itself a finding about the gene and the disease. The quoted sentences say what the papers report.
male infertility (4 papers, 2022 to 2024). The inability of the male to effect fertilization of an ovum after a specified period of unprotected intercourse. "Together, these data indicate that depletion of FBXO24 causes defective spermiogenesis, leading to male infertility." (PMID 38470475, 2024). "We first examined spermatogenesis to determine the cause of male infertility in Fbxo24 KO mice." (PMID 37986737, 2024). "Fbxo24 knockout (KO) mice exhibited malformed flagellar structures, impaired sperm motility, and male infertility, likely due to the accumulation of abnormal granules." (PMID 37986737, 2024). "Further, we deleted Fxbo24 using the CRISPR/Cas9 system and found that Fbxo24 KO mice exhibited abnormal flagellar structures and male infertility." (PMID 37986737, 2024).
breast carcinoma (2 papers, 2025). "In addition, FBXO24-mediated depletion of LSD1 level reduced breast cancer cell migration and invasion, which was associated with the increased expression of E-cadherin and reduced expression of Vimentin." (PMID 40940894, 2025). "The FBXO24-mediated depletion of LSD1 led to increased expression of CCL5 and CXCL10 in breast cancer cells, which was associated with increased level of H3K4me2 in the promoter regions of their genes." (PMID 40940894, 2025). "It was shown that FBXO24, an E3 ligase, catalyzed LSD1 ubiquitination in breast cancer cells." (PMID 40940894, 2025).
pneumonia (2 papers, 2024). An acute, acute and chronic, or chronic inflammation focally or diffusely affecting the lung parenchyma, caused by an infection in one or both of the lungs (by bacteria, viruses, fungi, or mycoplasma.). "In the process of studying ubiquitin associated proteins in pneumonia, human transplant rejected lung tissue testing positive in bacterial cultures had a significant increase in FBXO24 mRNA and protein levels compared to uninfected tissue or to other related F-box proteins." (PMID 39039092, 2024). "Further studies examining the kinetics of FBXO24 expression and DARS2 abundance in experimental pneumonia and in humans will elucidate the biological association for these proteins in host immunity." (PMID 39039092, 2024). "Last, in an experimental pneumonia model ex vivo studies suggest that partial disruption of the Fbxo24 gene in mice is sufficient to restore pulmonary mitochondrial function." (PMID 38735474, 2024). "During experimental pneumonia, Fbxo24 knockout mice exhibit elevated DARS2 levels with an increase in pulmonary cellular and cytokine levels." (PMID 39039092, 2024). "In this regard, in preliminary studies using a virtual homology structure-based design we have generated a tool compound that antagonizes FBXO24 activity (unpublished observations) that may be suitable for future in vivo testing in animal models of experimental pneumonia." (PMID 38735474, 2024). "To assess biological relevance of FBXO24 targeting of FOXK2, we pursued studies using Fbxo24+/− mice in a model of experimental pneumonia using K. pneumoniae." (PMID 38735474, 2024). "While FBXO24 immunosuppressive activity may be detrimental to pathogen clearance at early stages of infection, it may also protect against collateral tissue damage and aid in the resolution of inflammation in pneumonia similar to the purported functions of lipid mediators and interleukin 1039,40." (PMID 39039092, 2024).
bacterial pneumonia (1 paper, 2024). Acute infection of the lung parenchyma caused by bacteria (e.g., Streptococcus pneumoniae, Haemophilus influenzae, Chlamydia pneumoniae, Mycoplasma pneumoniae, and Legionella pneumophila). "In experimental bacterial pneumonia, Fbxo24 heterozygous mice exhibited preserved mitochondrial function and Foxk2 protein levels compared to WT littermates." (PMID 38735474, 2024).
E. coli infection (1 paper, 2024). "Likewise, unlike S. aureus, the bacterial pathogens K. pneumoniae, S. pneumoniae, and E. coli infection all increased FBXO24 protein expression in BEAS-2B cells or THP-1 cells." (PMID 39039092, 2024).
Infertility (1 paper, 2024). "As expected, we found that expression of the transgenic FBXO24 could rescue the defects in spermiogenesis and infertility observed in Fbxo24 KO male mice, which confirmed the specific targeting of Fbxo24 in the mutants and the true role of FBXO24 in spermiogenesis." (PMID 38470475, 2024).
infection (3 papers, 2014 to 2024). The state of being infected such as from the introduction of a foreign agent such as serum, vaccine, antigenic substance or organism. "FOXK2 disposal mediated by SCFFBXO24 during infections might be an opportunity to devise small molecule FBXO24 inhibitors that preserve FOXK2 levels." (PMID 38735474, 2024). "The data indicate that FBXO24 overexpression and PA103 infection differentially modulate FOXK2 phosphorylation, depending on the targeted residues." (PMID 38735474, 2024). "Infection of shRNAs against eight F-box proteins (FBXL5, FBXW5, FBXO3, FBXO4, FBXO5, FBXO24, FBXO25 and FBXO27) upregulated Snail1 protein levels (at least by 2-fold) compared with parental cells or cells infected with a control shRNA." (PMID 24157836, 2014). "BAL cell populations were not altered in WT versus Fbxo24 KO mice significantly after PA103 infection or LPS challenge." (PMID 39039092, 2024). "In contrast, immunoreactive levels of FOXK2, OPA1, MFF, and PHB1 generally were preserved in the majority of Fbxo24+/− mice regardless of infection." (PMID 38735474, 2024).
bacterial infection (2 papers, 2024). "In summary, the incomplete targeted disruption of FBXO24 in mice is sufficient to partially restore mitochondrial function and key associated bioenergetic proteins during bacterial infection." (PMID 38735474, 2024). "Given the robust increase in tissue injury and inflammation in Fbxo24 KO mice, we evaluated the effect of bacterial infection on lung function." (PMID 39039092, 2024). "Interestingly, while FBXO24 was observed to be induced in transplant-rejected lung samples positive for bacterial infection, we also observed increased plasma levels of DARS2 in infected patients." (PMID 39039092, 2024). "Hence, Fbxo24 KO mice have a striking increase in inflammatory responses with attendant lung injury after bacterial infection suggesting its role in suppressing innate immune pathways." (PMID 39039092, 2024).